CRYBA2 (crystallin beta A2)
Description:
Crystallins are the dominant structural components of the vertebrate eye lens.
Synonyms: CTRCT42
Tractability: No criterion of Open Targets' tractability assessment is met for any kind of drug.
Gene: Protein-coding gene on chromosome 2 (218,990,189 to 218,994,270, reverse strand). Ensembl gene ENSG00000163499.
Gene Ontology:
Molecular function: protein binding; structural constituent of eye lens; identical protein binding
Biological process: lens development in camera-type eye; visual perception
Genetic constraint (gnomAD): Loss-of-function variants: 20 observed, 21.18 expected, observed/expected ratio (o/e) 0.94, 90% interval 0.66 to 1.37. The upper end of that interval is the gene's LOEUF score, 1.37, which puts it in group 5 of 6, group 1 being the genes least tolerant of losing a copy. Missense variants: 271 observed, 274.43 expected, observed/expected ratio (o/e) 0.99, 90% interval 0.89 to 1.09. Synonymous variants: 101 observed, 112.32 expected, observed/expected ratio (o/e) 0.9, 90% interval 0.76 to 1.06.
Homologues: Orthologues: chimpanzee CRYBA2 (98% identical), rabbit CRYBA2 (92% identical), rat Cryba2 (92% identical), dog CRYBA2 (91% identical), guinea pig CRYBA2 (91% identical), mouse Cryba2 (91% identical), pig CRYBA2 (90% identical), macaque CRYBA2 (76% identical), tropical clawed frog cryba2 (64% identical), zebrafish cryba2b (56% identical), zebrafish cryba2a (55% identical). Paralogues in human: CRYBA1 (53% identical), CRYBA4 (53% identical), CRYBB1 (48% identical), CRYBB3 (43% identical), CRYBB2 (37% identical), CRYGA (30% identical), CRYGC (29% identical), CRYBG3 (29% identical), CRYGD (29% identical), CRYGS (29% identical), CRYBG1 (28% identical), CRYGB (28% identical), and 2 more.
Diseases named in the same sentence as CRYBA2 in open-access papers:
CRYBA2 is named in the same sentence as 11 diseases in open-access papers, as found by Europe PMC text mining. Sharing a sentence is not in itself a finding about the gene and the disease. The quoted sentences say what the papers report.
diabetes (2 papers, 2011 to 2018). "The observation of altered retinal crystallin expression with diabetes confirms our previous findings in this model and we therefore expanded our confirmation analysis to include crystallin isoforms Cryab and Cryba2." (PMID 21249158, 2011). "From our RNA sequencing analysis, it emerges that diabetes and the metabolic syndrome induce the expression of crystallin β (i.e. Crybb3, Cryba2, Cryba1) and γ (i.e. Crygc, Crygb, Crygf) in the retina, whereas we did not observe any significant effect on α crystallins." (PMID 30093686, 2018). "However, Crybb3, Cryba2, Crygc, Crygb, Crygf, Cryba1 were only upregulated in obese 42, indicating that their expression was likely affected by diabetes and metabolic diseases." (PMID 30093686, 2018).
congenital cataracts (1 paper, 2022). "A subset of the 7-days radiation only DEG (Cryaa, Cryba1, Cryba2, Cryba4, Crybb1, Crybb2, Crybb3, Crygs, Bsfp1) were enriched in nuclear and congenital cataracts, however, these genes were not dysregulated at 1 month or 4 months." (PMID 36207342, 2022).
pancreatic cancer (1 paper, 2020). "SCG5, CRYBA2, CPE and CHGB genes are associated with the prognosis of pancreatic cancer, and their low expression suggests a poor prognosis." (PMID 33164330, 2020). "Prognostic analysis showed the expression levels of four genes were significantly correlated with the overall survival time of patients with pancreatic cancer, namely SCG5, CRYBA2, CPE and CHGB." (PMID 33164330, 2020).
skin cancer (1 paper, 2018). "The vast heterogeneity of the sample collection with respect to diverse factors like platforms, origin, parts of the body, etc. positively influenced in the finding of 6 genes that had not previously related to skin cancer: SCGB2A1, CRYBA2, ANXA3, PCP4, SOSTDC1 and MYO15A." (PMID 29750795, 2018).
infection (1 paper, 2024). The state of being infected such as from the introduction of a foreign agent such as serum, vaccine, antigenic substance or organism. "In the LD strain, AICDA was significant, and in the Ross strain, CRYBA2 and SPI-C were the most significantly expressed genes among the transcripts following infection." (PMID 39342330, 2024).
CRYBA2 also shares sentences with these, for which no sentence is quoted: Age-related cataract (1 paper); cancer (1); cataract (1); meningioma (1); metabolic disease (1); metabolic syndrome (1).